MCCC1 (methylcrotonyl-CoA carboxylase subunit 1)
Description:
Biotin-attachment subunit of the 3-methylcrotonyl-CoA carboxylase, an enzyme that catalyzes the conversion of 3-methylcrotonyl-CoA to 3-methylglutaconyl-CoA, a critical step for leucine and isovaleric acid catabolism.
Synonyms: MCCA; MCCCα; MCC-B; MCCCalpha
Tractability: Small molecule: a structure with a bound ligand is known. PROTAC: ubiquitination databases record sites on it; its protein half-life has been measured.
Target class: Enzyme; Ligase
Gene: Protein-coding gene on chromosome 3 (183,015,218 to 183,116,075, reverse strand). Ensembl gene ENSG00000078070.
Subcellular location: Mitochondrion matrix
Subcellular location (Human Protein Atlas): Mitochondria
Pathways (Reactome):
Disease: 3-Methylcrotonyl-CoA carboxylase deficiency; Defective HLCS causes multiple carboxylase deficiency
Metabolism: Biotin transport and metabolism; Branched-chain amino acid catabolism
Gene Ontology:
Molecular function: methylcrotonoyl-CoA carboxylase activity; protein binding; biotin binding; biotin carboxylase activity; ATP binding; metal ion binding
Biological process: biotin metabolic process; branched-chain amino acid catabolic process; L-leucine catabolic process
Cellular component: methylcrotonoyl-CoA carboxylase complex; mitochondrial matrix; mitochondrion; cytosol
Genetic constraint (gnomAD): Loss-of-function variants: 52 observed, 80.03 expected, observed/expected ratio (o/e) 0.65, 90% interval 0.52 to 0.82. The upper end of that interval is the gene's LOEUF score, 0.82, which puts it in group 3 of 6, group 1 being the genes least tolerant of losing a copy. Missense variants: 774 observed, 900.87 expected, observed/expected ratio (o/e) 0.86, 90% interval 0.81 to 0.91. Synonymous variants: 307 observed, 315.1 expected, observed/expected ratio (o/e) 0.97, 90% interval 0.89 to 1.07.
Gene-disease validity (ClinGen):
ClinGen rates the evidence that MCCC1 causes each of these diseases.
3-methylcrotonyl-CoA carboxylase deficiency (autosomal recessive): Definitive.
Homologues: Orthologues: chimpanzee MCCC1 (99% identical), macaque MCCC1 (97% identical), dog MCCC1 (88% identical), mouse Mccc1 (84% identical), rat Mccc1 (83% identical), guinea pig MCCC1 (83% identical), pig MCCC1 (81% identical), rabbit MCCC1 (76% identical), tropical clawed frog mccc1 (72% identical), zebrafish mccc1 (70% identical), Drosophila melanogaster Mccc1 (53% identical), Caenorhabditis elegans mccc-1 (50% identical). Paralogues in human: PCCA (38% identical), PC (34% identical), ACACB (32% identical), ACACA (31% identical).
Diseases named in the same sentence as MCCC1 in open-access papers:
MCCC1 is named in the same sentence as 26 diseases in open-access papers, as found by Europe PMC text mining. Sharing a sentence is not in itself a finding about the gene and the disease. The quoted sentences say what the papers report.
Parkinson disease (9 papers, 2012 to 2025). A progressive degenerative disorder of the central nervous system characterized by loss of dopamine producing neurons in the substantia nigra and the presence of Lewy bodies in the substantia nigra and locus coeruleus. "For example, a case-control study of 1428 Han Chinese reported that the allele of MCCC1/LAMP3 (rs11711441) polymorphism is linked to a lower risk of Parkinson’s disease." (PMID 40170191, 2025). "Among them, the MCCC1 gene is involved in mitochondrial homeostasis and was shown to be associated with sporadic Parkinson’s disease in multiple GWAS; PM20D1 is associated with response to accumulation of amyloid-β in AD brains." (PMID 36109771, 2022). "The first large-scale meta-analysis of published genome-wide association studies (GWAS) in Parkinson’s disease (PD) identified 5 new genetic loci (ACMSD, STK39, MCCC1/LAMP3, SYT11, and CCDC62/HIP1R)." (PMID 24312176, 2013). "However, looking into our phenotypic data we can verify that CTD (SLC22A5), Parkinson ́s disease (LRPPRC), multiple sclerosis (IL4R), 3-MCCD (MCCC1), and different cancer types (FANCE, MAD1L1 and CD46) have been reported by the participants." (PMID 36404349, 2023).
bipolar disorder (1 paper, 2016). A disorder of the brain that causes unusual shifts in mood, energy, activity levels and the ability to carry out day-to-day tasks. "Few changes were identified following this treatment, although four proteins—FAM163A, RIN1, mTOR and MCCC1—shown to be dysregulated in bipolar disorder were dysregulated in the same direction by haloperidol treatment, suggesting that these effects may have been drug treatment-related." (PMID 27898073, 2016).
gastric cancer (1 paper, 2025). A primary or metastatic malignant neoplasm involving the stomach. "It suppresses the epithelial-mesenchymal transition through the SHH-GLI family zinc finger 1 (GLI1) pathway in hepatocellular carcinoma and through downregulation of the methylcrotonyl-CoA carboxylase subunit 1 (MCCC1) expression in malignant melanoma and gastric cancer." (PMID 40787625, 2025).
Hypoglycemia (1 paper, 2020). A decreased concentration of glucose in the blood. "Mutations in MCCC1 cause an autosomal recessive disease due to the loss of enzyme activity that manifests with hypoglycemia, ketonaemia, and severe metabolic acidosis." (PMID 32561715, 2020).
lung carcinoma (1 paper, 2025). "The anticancer activity of MCCC1-MTS against lung cancer was assessed using an A549 xenograft mouse model." (PMID 40943465, 2025).
neuroblastoma (1 paper, 2020). Neuroblastoma (NB) is the most common solid, extracranial childhood tumor. "In human neuroblastoma SH-SY5Y cells, like in HeLa cells, MCCC1 depletion increased LC3-II levels in both basal and BAF-treatment conditions." (PMID 32561715, 2020).
pancreatic cancer (1 paper, 2025). "In Panc-1 human pancreatic cancer cells, cytotoxicity was observed only with MCCC1-MTS at 150 μg/mL." (PMID 40943465, 2025).
sarcopenia (1 paper, 2022). Progressive decline in muscle mass due to aging which results in decreased functional capacity of muscles. "The most significant DMR associated with sarcopenia was located within the MCCC1 gene, a mitochondrial enzyme, which catalyses the carboxylation of 3‐methylcrotonyl CoA to 3‐methylglutaconyl CoA, a critical step in leucine catabolism." (PMID 34862756, 2022). "Sarcopenia was associated with 141 DMRs (Stouffer < 0.05), with the top DMR located within the promoter region of the Methylcrotonyl‐CoA Carboxylase 1 (MCCC1) gene, consisting of 13 CpGs (Stouffer = 3.62 × 10−12)." (PMID 34862756, 2022).
viral infection (1 paper, 2016). "The results indicated that MAVS knockdown significantly inhibited MCCC1-induced IFN promoter induction, suggesting that the MCCC1-mediated upregulation of IFNs upon virus infection is MAVS-dependent." (PMID 27629939, 2016). "The results showed that MCCC1-KD cells expressed much lower levels of cytokine mRNA than Scr.-KD cells upon virus infection." (PMID 27629939, 2016).
cancer (4 papers, 2018 to 2025). A tumor composed of atypical neoplastic, often pleomorphic cells that invade other tissues. "In addition, MCCC1-MTS markedly reduced the viability of multiple cancer cell lines with minimal cytotoxicity toward HaCaT cells and effectively suppressed the growth of A549-xenografted tumors in BALB/c nude mice without inducing weight loss." (PMID 40943465, 2025). "In this study, MCCC1-MTS selectively bound to cancer cell membranes and induced pore formation." (PMID 40943465, 2025). "MCCC1-MTS treatment led to cancer cell death and showed in vivo efficacy without inducing toxicity in normal tissues." (PMID 40943465, 2025). "Six genes (SLCO2A1, MGAT4B, SLC25A33, MCCC1, OIP5, and CTHRC1) have been shown to affect the tumorigenesis of other cancer types but not PC." (PMID 30024105, 2018).
infection (1 paper, 2021). The state of being infected such as from the introduction of a foreign agent such as serum, vaccine, antigenic substance or organism. "In the PRV- and mock-infected groups, 241 differentially expressed proteins (DEPs) were identified, 162 upregulated and 79 downregulated proteins at 24 h post-infection (hpi), among which AFP, Vtn, Hsp40, Herc5, and Mccc1 may play important roles in PRV propagation." (PMID 34680952, 2021).
tumor (1 paper, 2025). "Intravenous administration of MCCC1-MTS at 20 mg/kg in A549-xenografted mice resulted in effective tumor suppression without body weight loss." (PMID 40943465, 2025). "In contrast, MCCC1-MTS administered at 20 mg/kg inhibited tumor growth without causing weight loss." (PMID 40943465, 2025).
MCCC1 also shares sentences with these, for which no sentence is quoted: 3-methylcrotonyl-CoA carboxylase deficiency (1 paper); Alpers disease (1); breast carcinoma (1); cerebral malaria (1); coenzyme Q10 deficiency (1); hepatocellular carcinoma (1); infectious disease (1); Leigh syndrome (1); malaria (1); malignant melanoma (1); medium chain acyl-CoA dehydrogenase deficiency (1); multiple sclerosis (1); short chain acyl-CoA dehydrogenase deficiency (1); Stroke (1).